TG (thyroglobulin)
Diseases named in the same sentence as TG in open-access papers (continued):
Sharing a sentence is not in itself a finding about the gene and the disease.
autoimmune disease (49 papers, 2005 to 2025). A disorder resulting from loss of function or tissue destruction of an organ or multiple organs, arising from humoral or cellular immune responses of the individual to their own tissue constituents. "TPO and anti-thyroglobulin antibodies were strongly associated with the presence of autoimmune disease in persons with DS/MMS (p < 0.001, 95%CI: 2.46–44.8) and DS (p < 0.001, 95%CI: 3.56–11.4) but not MMD (p = 0.44, 95%CI:0.4–35.4)." (PMID 34566869, 2021). "HT is an autoimmune disease caused by antibodies to thyroid peroxidase, thyroglobulin, and/or thyroid stimulating hormone receptors causing an antibody-dependent cellularly mediated cytotoxicity of the thyroid." (PMID 32775036, 2020). "Both autoimmune diseases involve the abnormal activation of T and B lymphocytes, which leads to the production of specific autoantibodies: anti-thyroperoxidase and anti-thyroglobulin in HT and anti-desmogleins in pemphigus." (PMID 41552158, 2025). "HT is the most common autoimmune disease globally, and it is characterized by chronic inflammation, increased circulating concentrations of autoantibodies against thyroid peroxidase and thyroglobulin, and tertiary lymphoid follicle development." (PMID 36817926, 2023). "TGAb, defined as thyroglobulin antibody, is a major thyroid-specific protein and mistakenly attacks healthy organs and tissues in autoimmune diseases." (PMID 34594299, 2021). "This patient’s manifestation of disease with rapid progression and elevated thyroglobulin also supports the argument of sarcoidosis as an autoimmune disease." (PMID 34631064, 2021). "For DTC patients with autoimmune disease or post-trauma immune system response, the evaluation efficiency of Tg is greatly reduced due to interference of thyroglobulin antibody (TgAb)." (PMID 32655554, 2020). "Despite detailed data regarding the role of specific Cts in tumor disease, this family of proteases counts 11 members with redundant and compensatory activities, as shown in autoimmune diseases and or thyroglobulin processing, respectively." (PMID 32455715, 2020). "Identification as an autoimmune disease follows observations that lymphocytes infiltrate the thyroid and autoantibodies against thyroglobulin, thyroid peroxidase, and (rarely) thyroid hormone stimulating receptor are found in patients with HT." (PMID 16280086, 2005). "This may increase susceptibility to autoimmune disorders compared to the general population, helping to explain both the higher frequency and elevated levels of anti-TPO and anti-TG antibodies observed in these patients." (PMID 40806651, 2025). "A survey of autoimmune diseases and autoantibodies, including anti-thyroid peroxidase antibody (anti-TPO), anti-thyroglobulin antibody (ATA), anti-mitochondrial antibody, anti-nuclear antibody, and anti-ds DNA, was negative." (PMID 36851302, 2023). "Additionally, although other autoimmune diseases related to the thyroid gland have been documented as being associated with T1D, only two patients with T1D (2.6%) demonstrated positive thyroglobulin antibody (TGAb), but were negative for thyrotrophin receptor antibodies (TRAb) and TPO antibodies." (PMID 36835954, 2023). "All the patients were examined for autoimmune disease symptoms and tested for the presence of antithyroperoxidase (anti-TPO) and antithyreoglobulin (anti-TG) antibodies." (PMID 31417494, 2019). "These include antibodies specific to autoimmune diseases, e.g., anti-thyroid peroxidase (anti-TPO), anti-thyroglobulin (anti-TG), and antinuclear antibodies (ANAs), as well as those that are non-specific, such as anti-malondialdehyde-modified human serum albumin (anti-HSA-MDA) or anti-α-crystallin." (PMID 40943118, 2025). "The ISPED/SIEDP suggests measuring TSH, FT4, FT3, anti TPO and anti TG in case of autoimmune disease, however without specifying when to test." (PMID 40230804, 2025).
autoimmune disease (continued). "Relevant risk factors such as thyroid peroxidase antibodies (TPOAb), TSH receptor antibodies (TRAb), thyroglobulin antibodies (TgAb), and pre-existing autoimmune diseases were not collected." (PMID 38598052, 2024). "Thyroid autoimmunity (TAI), the most common autoimmune disorder in women of reproductive age, is defined as the detection of thyroid peroxidase antibodies (TPO-Ab), thyroglobulin antibodies (Tg-Ab), or both, in the serum, which may be accompanied by clinical or subclinical thyroid dysfunction." (PMID 38596217, 2024). "Since the EAT mouse model has been established only through immunization by murine thyroglobulin and Freund adjuvant, the production of ENO1Ab may be secondary to the autoimmune responses against thyroid tissue other than the concurrent non-organ specific autoimmune disorders." (PMID 36674531, 2023).
depression (48 papers, 2005 to 2026). "Further, the detection of anti-thyroid peroxidase and anti-thyroglobulin autoantibodies in the cerebrospinal fluid of patients with unipolar depression reinforces the potential role of immune mechanisms in psychiatric conditions beyond thyroid dysfunction." (PMID 39717384, 2024). "Participants and methods: Paired serum and CSF samples from 100 patients with unipolar depression were examined for anti-TPO and anti-TG antibodies using enzyme-linked immunosorbent assays." (PMID 32726952, 2020). "Depression, anxiety and positive symptoms were significantly greater, and blood pressure (SBP, DBP), BMI, lipids (TC, TG, HDL, LDL), thyroid hormones (TSH, TgAb, TPOAb), and FBG were all higher in patients with FSA in the past 14 days than those who did not attempt suicide (p < 0.05)." (PMID 38585486, 2024).
thyroid nodule (46 papers, 2012 to 2026). A small circumscribed mass in the THYROID GLAND that can be of neoplastic growth or non-neoplastic abnormality. "Moreover, the association of thyroid nodules with serum thyroid hormones and thyroglobulin levels significantly varies, making these markers unreliable predictors of existing thyroid nodules." (PMID 38068463, 2023). "In addition, one study noted that thyroid nodules detected by ultrasound or the presence of diffuse goiter and elevated serum thyroglobulin are findings associated with an increased risk of TCA." (PMID 25780482, 2015). "It has been reported that serum thyroglobulin antibody was an independent predictor for thyroid malignancy in thyroid nodules." (PMID 25179111, 2014). "Analysis via the receiver operating characteristic (ROC) curve indicated that thyroglobulin (Tg) is of diagnostic value for distinguishing between the presence and absence of thyroid nodules." (PMID 41377937, 2025). "This study aims at evaluating whether preoperative thyroglobulin antibody (TgAb) levels increase the likelihood that a thyroid nodule is malignant." (PMID 27179632, 2016). "Sometimes the diagnosis may be less clear, particularly when the primary presenting symptom is a solitary thyroid nodule in conjunction with normal thyroid function, thyroglobulin levels, and a normal ESR." (PMID 24397799, 2014). "Using a combination of at least two-marker gene sets, a specificity of up to 87% (LGALS3/HGD1) and a sensitivity of up to 82% (LGALS3/TG) emphasises that molecular analysis of FNAB is a promising tool to improve the differential diagnosis of thyroid nodules (Hegedüs, 2010)." (PMID 22223087, 2012). "Patients presenting with thyroid nodules are evaluated for levels of serum thyroid stimulating hormone (TSH), free triiodothyronine (fT3) and thyroxine (fT4), thyroglobulin (TG), and anti-thyroid peroxidase antibody (ATPO)." (PMID 27802347, 2016). "Serum growth differentiation factor 15, thyroid function, thyroid autoantibodies, thyroglobulin and other biochemical indicators were measured and compared between thyroid nodule positive and negative groups." (PMID 28489602, 2017). "It was found in the study that there was a statistically significant difference between the thyroglobulin levels of the patients with thyroid nodules and the thyroglobulin levels of the patients without nodules, which might be associated with these conditions." (PMID 39024360, 2024). "Moreover, differences between thyroid function indicators with and without thyroid nodules were compared to explore whether the detection of thyroglobulin (Tg) levels has certain significance for the diagnosis of thyroid nodules." (PMID 41377937, 2025).
Autoimmunity (37 papers, 2005 to 2025). The occurrence of an immune reaction against the organism's own cells or tissues. "Thus, gut dysbiosis might be related to the immune system development in AITD patients and the loss of tolerance to self-antigens including thyroglobulin and the autoimmunity that triggers AITD." (PMID 33114469, 2020). "It is now well established that GD, B, and T lymphocyte-mediated autoimmunity are known to be directed against four well-known thyroid antigens: thyroglobulin (Tg), thyroid peroxidase (TPO), sodium-iodide symporter (NIS) and the thyrotropin receptor (TSH-R)." (PMID 29449887, 2018). "The rise of the thyroglobulin antibodies and anticardiolipin antibody indicated abnormal autoimmunity." (PMID 28191358, 2017). "The detection in these patients of IgE autoantibodies against various antigens, such as tissue factor or interleukin (IL)-24, staphylococcal exotoxins, double-stranded DNA, thyroglobulin, and thyroperoxidase, indicates a possible type I autoallergy or autoimmunity." (PMID 35744079, 2022). "This hormonal regulation is considered important for the suppression of autoimmunity during hormonally induced changes in thyroid cell function, which results in an enhanced expression of potential thyroid autoantigens, such as thyroglobulin, thyroid peroxidase, and the TSH receptor." (PMID 34938270, 2021). "However, when this tolerance is broken, autoimmunity occurs, resulting in the production of autoantigens such as thyroid peroxidase (TPO), thyroglobulin (Tg) and thyroid-stimulating hormone (TSH) receptor (TSH-R)." (PMID 36835987, 2023). "Screening for autoimmunity was performed, measuring anti-ovarian antibodies, anti-thyroid antibodies (anti-thyroperoxydase (TPO) and anti-thyroglobulin (TG) antibodies), anti-adrenal antibodies, anti-gastric parietal cells antibodies and antitissue transglutaminase (tTG) antibodies." (PMID 34187539, 2021).
Insulin resistance (36 papers, 2013 to 2025). Increased resistance towards insulin, that is, diminished effectiveness of insulin in reducing blood glucose levels. "HOMA-IR: homeostatic model assessment-insulin resistance, TSH: thyroid-stimulating hormone, TPO: thyroid peroxidase, Tg: thyroglobulin." (PMID 38094874, 2023).
Hypertension (35 papers, 2008 to 2025). The presence of chronic increased pressure in the systemic arterial system. "The levels of serum FT3, FT4, urinary iodine and urine iodine/creatinine ratio showed a significant diminishing trend while serum thyroglobulin showed an increasing trend with the severity of hypertensive disease in pregnancy." (PMID 35120491, 2022). "In addition, low urinary iodine concentration, low serum thyroxine and high serum thyroglobulin were independent predictors of hypertensive disease in pregnancy in the study population." (PMID 35120491, 2022). "The patient with RR-DTC experienced abdominal, back, and neck pain as well as acne, diarrhea, hypertension, hypertriglyceridemia, hyperuricemia, insomnia, pyrexia, and increased thyroglobulin; all were non-serious AEs." (PMID 34562750, 2021).
thyroid tumor (34 papers, 2000 to 2025). A benign or malignant neoplasm affecting the thyroid gland. "Emerging evidence suggests that serum thyroglobulin (Tg) levels correlate with both the secretory activity and malignant potential of thyroid tumors, with FTC typically exhibiting elevated Tg secretion." (PMID 40708719, 2025). "It is reported that TTF-1 and TG are demonstrable through immunohistochemical methods in approximately 75% of thyroid tumors." (PMID 40575170, 2025). "Biochemical testing with thyroid tumor markers (thyroglobulin and anti-thyroglobulin antibodies), as well as imaging with SPECT/CT, are helpful initial tools following WBS." (PMID 39372828, 2024). "Primary thyroid tumors of follicular origin stain positive for thyroglobulin (TG) and thyroid transcription factor-1 (TTF-1)." (PMID 37990226, 2023). "The incomplete resection of normal thyroid tissue or the dedifferentiation of thyroid tumors can render the interpretation of thyroglobulin extremely challenging." (PMID 32748840, 2020). "Positive staining with anti-thyroglobulin and anti-calcitonin antibodies would favor a primary thyroid tumor." (PMID 31764826, 2019). "Because of similarity between the neuroendocrine tumor and a thyroid tumor-specifically, follicular-like characteristics-immunohistochemical stains for thyroglobulin, TTF1, and calcitonin were performed." (PMID 28316853, 2017). "The thyroid tumors are usually reactive for immunohistochemical markers of thyroglobulin and thyroid transcription factor-1 (TTF-1)." (PMID 25685581, 2015). "Primary thyroid neoplasm will express thyroglobulin, thyroid transcription factor-1, and/or calcitonin, while these antibodies will be negative in ACC and most other tumors of extra thyroid origin." (PMID 20931039, 2010). "Thyroid tumors derived from follicular cells routinely stain positively for thyroglobulin." (PMID 35681825, 2022). "A positive immunostaining for thyroglobulin suggests the diagnosis of a primary thyroid neoplasm, although a primary thyroid neoplasm may still be present with negative immunostaining." (PMID 24455357, 2013). "Namely, the detection of immunopositive staining for thyroglobulin and the thyroid transcription factor-1 (TTF-1) can indicate primary thyroid neoplasms." (PMID 39050581, 2024). "In mice, thyroglobulin (TG), the thyroid prohormone and main constituent of follicular colloid, is consistently downregulated in BRAFV600E-driven thyroid tumors, featuring a poorly differentiated state." (PMID 34379110, 2022). "Melan-A, inhibin, and some other markers have been found to be positive in patients with ACC, and thyroglobulin and TTF-1 have been found to be positive in patients with thyroid neoplasms in immunohistochemical studies." (PMID 23889916, 2013). "Differential diagnosis with secondary thyroid tumors depends on non-reactivity to immunohistochemical (IHC) markers for TFCC (thyroglobulin - TG and TTF1)." (PMID 31063281, 2019). "Deregulation of thyroglobulin in PTC was previously reported, however, the impact of this phenomenon on thyroid tumor progression remains unknown." (PMID 28855631, 2017). "Negativity for TTF1 and thyroglobulin ruled out thyroid neoplasm." (PMID 28003924, 2016). "Furthermore, immunoperoxidase stains for thyroglobulin and TTF-1 were negative, excluding the possibility of a thyroid neoplasm." (PMID 15943858, 2005). "In this regard, immunohistochemistry for thyroglobulin (which may, however, be negative in anaplastic thyroid carcinoma) and TTF-1 (more specific) is very useful in distinguishing primary (positive) from secondary (negative) thyroid tumors." (PMID 25628901, 2015).
lymph node metastasis (32 papers, 2013 to 2026). "LASSO regression identified eight predictors: age, tumor size, extrathyroidal extension, lymph node metastasis, BRAF V600E mutation, postoperative stimulated thyroglobulin (sTg) level, radioactive iodine dose, and TNM stage." (PMID 41877795, 2026). "The results revealed that lymph node metastasis count and thyroglobulin (Tg) were the most influential variables contributing to the prediction of 131I-WBS outcomes." (PMID 41393114, 2025). "Non-excellent response at 1-year follow-up were associated with preoperative thyroid-stimulating hormone levels, lymph node metastasis, number of metastatic lymph nodes, and first stimulated thyroglobulin." (PMID 40900471, 2025). "When cytology and/or thyroglobulin levels in the needle washout fluid are in favor of lymph node metastases (LNM), in the setting of first-line therapy a therapeutic neck dissection is recommended." (PMID 40361424, 2025). "This study conducted at Zhejiang Cancer Hospital provided important insights into predicting 131I-WBS outcomes using logistic regression models based on significant predictors such as lymph node metastases count counts and thyroglobulin levels." (PMID 41393114, 2025). "High-risk disease was defined according to the 2015 ATA guidelines as gross extrathyroidal extension, lymph node metastasis >3 cm, postoperative elevated serum thyroglobulin, distant metastases, and/or positive resection margins." (PMID 39456540, 2024). "High pre-ablation stimulated thyroglobulin (presTg), presence of lymph node metastasis, male gender and delayed initial RAI therapy (≥3 months) after thyroidectomy were significant independent predictors of BIR." (PMID 38696058, 2024). "Other factors included in the rules were BMI, anti-thyroglobulin antibody, fT4, central and lateral lymph node metastasis, cancer size, and postoperative TSH level." (PMID 34678881, 2021). "Age, gender, tumor size, histology, multifocality, vascular invasion, extrathyroidal extension, presence and number of lymph node metastasis, and stimulated thyroglobulin at ablation (sTg) were evaluated." (PMID 34033287, 2021). "In the postoperative follow-up, the thyroglobulin and antithyroglobulin values are important markers for lymph node metastasis and are useful in planning radioactive iodine (RAI) treatment." (PMID 28331494, 2017). "Non-low risk of recurrence were associated with Bethesda V/VI cytology, lymph node dissection, angiolymphatic and tumor capsule invasion, extrathyroidal extension, lymph node metastasis, number of metastatic lymph nodes, first stimulated thyroglobulin, and radioiodine dose." (PMID 40900471, 2025). "Ultrasound-guided fine needle aspiration thyroglobulin (FNA-Tg) is recommended for the diagnosis of lymph node metastasis (LNM) in differentiated thyroid cancer (DTC), but its optimal cutoff value remains controversial, and the effect of potential influencing factors on FNA-Tg levels is unclear." (PMID 38529394, 2024). "Finally, as expected, patients with lymph node metastasis during the follow-up also had a higher thyroglobulin curve." (PMID 36765899, 2023). "In previous studies, serum thyroglobulin could generally be assessed by lymph node puncture before surgery to determine the status of lymph node metastasis or tumor recurrence after surgery." (PMID 35250865, 2022). "Our research found that patients with younger age (<14 years) were predominantly multifocal and have positive preoperative thyroglobulin (Tg) and higher recurrence rate, and their number of lymph node metastases (LNMs) was more than that of the older group (14–18 years)." (PMID 35280803, 2022). "In addition, measurement of thyroglobulin in washout fluid increases specificity and sensitivity of lymph node metastasis." (PMID 34248851, 2021). "Decrease in thyroglobulin (TG) and antithyroglobulin (anti-TG) values which are used in the postoperative follow-up of these patients is one of the most important indicators of possible lymph node metastasis." (PMID 28331494, 2017).